RMDN1 (regulator of microtubule dynamics 1)
Synonyms: RMD-1; FAM82B; CGI-90; FLJ20665; RMD1
Tractability: PROTAC: ubiquitination databases record sites on it; its protein half-life has been measured.
Gene: Protein-coding gene on chromosome 8 (86,468,257 to 86,514,357, reverse strand). Ensembl gene ENSG00000176623.
Subcellular location: Cytoplasm; Cytoplasm, cytoskeleton, spindle; Cytoplasm, cytoskeleton, spindle pole
Subcellular location (Human Protein Atlas): Centrosome; Actin filaments
Gene Ontology:
Molecular function: microtubule binding
Biological process: attachment of mitotic spindle microtubules to kinetochore; mitotic spindle organization
Cellular component: centrosome; mitochondrion; mitotic spindle pole; spindle microtubule; cytoplasm; spindle; spindle pole
Genetic constraint (gnomAD): Loss-of-function variants: 16 observed, 19.9 expected, observed/expected ratio (o/e) 0.8, 90% interval 0.54 to 1.22. The upper end of that interval is the gene's LOEUF score, 1.22, which puts it in group 5 of 6, group 1 being the genes least tolerant of losing a copy. Missense variants: 232 observed, 193.77 expected, observed/expected ratio (o/e) 1.2, 90% interval 1.08 to 1.34. Synonymous variants: 84 observed, 74.98 expected, observed/expected ratio (o/e) 1.12, 90% interval 0.94 to 1.34.
Homologues: Orthologues: chimpanzee RMDN1 (99% identical), macaque RMDN1 (96% identical), pig RMDN1 (88% identical), dog RMDN1 (86% identical), rabbit RMDN1 (83% identical), mouse Rmdn1 (81% identical), rat Rmdn1 (81% identical), tropical clawed frog rmdn1 (55% identical), zebrafish rmdn1 (49% identical), Caenorhabditis elegans F33H2.6 (32% identical). Paralogues in human: RMDN3 (31% identical), RMDN2 (27% identical), TEX10 (17% identical).
Diseases named in the same sentence as RMDN1 in open-access papers:
RMDN1 is named in the same sentence as 6 diseases in open-access papers, as found by Europe PMC text mining. Sharing a sentence is not in itself a finding about the gene and the disease.
RMDN1 shares sentences with these, for which no sentence is quoted: cancer (1 paper); colon cancer (1); colorectal cancer (1); cutaneous melanoma (1); lung adenocarcinoma (1); tumor (1).